TREM2 (triggering receptor expressed on myeloid cells 2)
Diseases named in the same sentence as TREM2 in open-access papers (continued):
Sharing a sentence is not in itself a finding about the gene and the disease.
glioma (continued). "According to these observations, TREM2 may serve as a biomarker for mesenchymal subtype glioma due to its highly specific expression in mesenchymal subtype gliomas." (PMID 36713360, 2022). "TREM2 was discovered to be an independent prognostic factor in glioma." (PMID 36713360, 2022). "Based on our findings, we hypothesized that TREM2 might modulate the expression of immunological checkpoints to assist glioma cells in maintaining malignant phenotypes." (PMID 36713360, 2022). "Uncertain is the function of TREM2 in glioma and tumor immune responses." (PMID 36713360, 2022). "Our findings have shown that TREM2 expression is related to glioma malignant phenotype." (PMID 36713360, 2022). "Thus, it is expected that small-molecule medications targeting TREM2 or monoclonal antibodies would enhance the efficacy of glioma immunotherapy." (PMID 36713360, 2022). "The results showed that TREM2 was highly expressed in GBM and LGG tissues rather than normal tissues or any other tumor types, indicating that TREM2 may play a carcinogenic role in glioma." (PMID 36713360, 2022). "The TREM-1/TREM-2 ratio that expression on the surface of blood monocytes could help predict prognosis in patients with gliomas." (PMID 34176389, 2021). "We showed that the TREM-1/TREM-2 ratio (expression on the surface of blood monocytes) could help predict prognosis in patients with gliomas, especially in high-grade gliomas, and that systemic inflammation has an impact on the patient's overall survival." (PMID 32684831, 2020). "Upregulation of TREM2 enhanced capacity of proliferation and invasion in glioma cells." (PMID 30683932, 2019). "Our data affirmed that knockdown of TREM2 remarkably inhibited growth, migration and invasion of glioma cells, while ectopic expression of TREM2 showed a lower expression glioma cell line, SHG44, promoted cell proliferation, migration and invasion." (PMID 26506595, 2016). "In our study, TREM2 knockdown significantly suppressed the expression of CXCL10 and CXCR3, which could be interpreted as anti-proliferation and anti-invasion effects of TREM2 siRNA in glioma cells." (PMID 26506595, 2016). "Furthermore, TREM2 expression was closely related to pathological grade and overall survival of patients with gliomas." (PMID 26506595, 2016). "In summary, our study suggests that TREM2 may work as an oncogene and a new effective therapeutic target for glioma treatment." (PMID 26506595, 2016). "Our results suggested a role of TREM2 in the promotion of glioma invasion." (PMID 26506595, 2016). "In addition, TREM2 was found to be highly expressed in glioma-associated microglia/macrophages (GAMs) in glioma tissues and had a negative correlation with patient survival time." (PMID 38725629, 2024). "Knockdown of TREM2 can reduce the polarization of M2 phenotype, causing TAMs to remodel into the M1 type, which exhibits a pro-inflammatory and immunostimulatory state, inhibits the growth as well as invasiveness of hepatic cell carcinoma (HCC) and glioma cells, and suppresses tumor progression." (PMID 38725629, 2024). "In addition, gliomas with limited tumor purity demonstrated elevated TREM2 expression." (PMID 36713360, 2022). "As a result, TREM2 may serve as a potential prognostic predictor for glioma patients." (PMID 36713360, 2022). "Thus, the increased expression of TREM2 may be related to the fast growth, invasiveness and migration potential of gliomas." (PMID 26506595, 2016). "The exact pathway that TREM2 may regulate in gliomas remains unclear." (PMID 26506595, 2016). "Therefore, TREM2 may be considered as an oncogene and has significant value as an unfavorable progression indicator for glioma patients, and may serve as a therapeutic target in the future." (PMID 26506595, 2016). "First, compared to WHO II and WHO III gliomas, we found that WHO IV GBM patients had relatively higher TREM2 expression in the three databases, demonstrating that high TREM2 expression was predictive of high malignancy of glioma." (PMID 36713360, 2022).
glioma (continued). "However, the role of TREM2 in glioma and tumor immune responses remains unclear." (PMID 36713360, 2022). "This work suggests epithelial TREM2 contributes to oncogenic activity in the context of RCC and glioma." (PMID 36119485, 2022). "In our cohort of glioma patients, we found that the serum levels of HMGB1 negatively correlated with the percentage of TREM-1+ Mo and with the TREM-1/TREM-2 ratio." (PMID 32684831, 2020). "In 63 adult patients with gliomas and 31 healthy controls, the expressions of TREM-1 and TREM-2 on CD14+ blood cells (method: flow cytometry) and the levels of soluble sTREM-1, HMGB1, IL-6, and IL-10 (Elisa tests) were analyzed." (PMID 32684831, 2020). "High expression (more than 25% of positive-stained tumor cells), low expression (less than 25% of positive-stained tumor cells) and non-expression of TREM2 was observed in 41, 23 and 6 cases of glioma, respectively." (PMID 26506595, 2016). "Here, we reported that TREM2 was significantly overexpressed in glioma tissues compared with non-tumorous brain tissues." (PMID 26506595, 2016). "In the present study, we found that TREM2 expression was increased in glioma tissues compared with normal brain tissues, which was supported by glioma patients' data from TCGA." (PMID 26506595, 2016). "In addition, the absence of TREM2 hampers the capacity of myeloid cells within glioma to engulf tumor cells." (PMID 39135069, 2024). "We found a negative correlation of the serum levels of HMGB1 in glioma patients with both percentages of CD14+ TREM-1+ cells (P = 0.049) and TREM-1/TREM-2 ratio (P = 0.004)." (PMID 32684831, 2020).
multiple sclerosis (31 papers, 2013 to 2025). A progressive autoimmune disorder affecting the central nervous system resulting in demyelination. "A previous investigation associated with experimental multiple sclerosis demonstrated that upregulation of TREM2 in bone marrow‐derived myeloid precursor cells augmented lysosomal and phagocytic activity." (PMID 38649789, 2024). "Other studies have implicated TREM2 in the phagocytosis of apoptotic material both in vitro and in experimental autoimmune encephalomyelitis, an animal model for multiple sclerosis." (PMID 23855984, 2013). "Although downregulating TREM2 expression or reducing CSF sTREM2 levels could be a therapeutic target for individuals with FTD secondary to GRN mutations, animal models of multiple sclerosis deteriorated with TREM2 inhibition." (PMID 30111356, 2018). "In the last years, several members of the immunoglobulin superfamily such as CD200R, TREM-2 or SIGLECs have been reported to be key regulators of microglial activation, and its dysfunction has been implicated in different CNS pathologies such as Multiple Sclerosis or Alzheimer’s Disease." (PMID 25927603, 2015). "More importantly, TREM2 activation promotes myelin debris clearance and improves remyelination after multiple sclerosis." (PMID 38649789, 2024). "A study has demonstrated that in patients with multiple sclerosis (MS), TREM2 expression is elevated both at the mRNA and protein levels in active MS lesions." (PMID 37013543, 2023). "TREM2-transduced myeloid precursors mediate nervous tissue debris clearance and facilitate recovery in an animal model of multiple sclerosis." (PMID 31749696, 2019). "TREM2 suppresses the inflammatory response in vitro by repression of microglia-mediated cytokine production and secretion, and the anti-inflammatory effect of TREM2 was shown in an animal model of multiple sclerosis." (PMID 28592261, 2017). "In other words, sTREM2 may be involved in multiple sclerosis by inhibiting the presumed regulatory function of TREM2 ligation on myeloid cells." (PMID 35382840, 2022). "The role of TREM2 is widely studied, not only in AD, but different studies suggest that it may be involved also in the pathophysiology of multiple sclerosis (MS)." (PMID 33652870, 2021). "Despite TREM2 phagocytic role has been extensively studied in acute and chronic neurodegenerative diseases models as AD or multiple sclerosis; to the best of our knowledge, this is the first study showing a link of TREM2 with phagocytic microglia after direct or primary acute axonal injury." (PMID 33328887, 2020). "Moreover, MS patients treated with natalizumab, an immune-modulating drug, showed an improvement in the clinical course correlated with a significant decrease in the CSF soluble TREM2 (sTREM2) supporting the crucial role of microglia in the pathophysiology of multiple sclerosis." (PMID 33652870, 2021). "These include, for example, marker genes for disease-associated microglia (DAM), the microglia neurodegenerative phenotype (MGnD), and microglia inflamed in multiple sclerosis (e.g., APOE, CLEC7A, TREM2, CD68)." (PMID 40700130, 2025). "Similarly, human and animal data show that exercise can increase TREM2 levels in CSF of AD patients, maintain plasma TREM2 levels in APP/PS1 mice, and reduce plasma GFAP levels in multiple sclerosis patients." (PMID 36935511, 2023). "Research has demonstrated that TREM2 limits tissue destruction and facilitates repair within the CNS by clearing cellular debris during experimental autoimmune encephalomyelitis (EAE), an animal model of multiple sclerosis." (PMID 36463233, 2022). "TREM-2 is expressed by microglia in the CNS both during normal development in mice and in experimental autoimmune encephalomyelitis (EAE) - a mouse model of multiple sclerosis (a white-matter disease)." (PMID 25187205, 2014).
Sepsis (28 papers, 2016 to 2025). Sepsis is defined as life-threatening organ dysfunction caused by a dysregulated host response to infection. "For instance, during the tumultuous course of sepsis and its associated acute lung injury, the activation of TREM2 amplifies phagocytic activity and cultivates an anti-inflammatory milieu, potentially mitigating the severity of injury." (PMID 40552184, 2025). "This review endeavors to illuminate the role of TREM2 in the context of acute lung injury associated with sepsis." (PMID 40552184, 2025). "Recent studies on myocardial infarction, sepsis-induced cardiomyopathy, and hypertensive heart failure also implicated the protective role of TREM2 signaling in cardiac macrophages through efferocytosis and paracrine functions." (PMID 40083551, 2025). "TREM2 expression is upregulated in monocytes/macrophages and is associated with disease severity in sepsis." (PMID 39405126, 2024). "In a mouse model of nonalcoholic fatty liver disease (NAFLD)-associated sepsis, TREM2 deficiency accelerated the progression of NAFLD and subsequent susceptibility to sepsis." (PMID 39113887, 2024). "To assess the association between TREM2 and sepsis progression, we next analyzed the correlations between TREM2 expression and laboratory diagnostic markers indicative of disease severity of sepsis patients." (PMID 39405126, 2024). "Meanwhile, TREM2+ monocytes/macrophages displayed a lipid-associated and inflammatory phenotype in the context of sepsis." (PMID 39405126, 2024). "Subsequently, to explore the differential diagnostic potential of TREM2 expression in sepsis, we divided patients into groups based on the pathogen species and analyzed TREM2 expression levels." (PMID 39405126, 2024). "Consistently, we identified a population of TREM2+ LAMs in sepsis and demonstrated that TREM2 deficiency decreased triglyceride levels and facilitated FAO in sepsis." (PMID 39405126, 2024). "Collectively, we investigated the in vivo role of TREM2 in sepsis and demonstrated that TREM2 deficiency protected mice from sepsis." (PMID 39405126, 2024). "In summary, this study explored the role of TREM2 in sepsis and elucidated that TREM2 deficiency ameliorated sepsis by restoring impaired FAO." (PMID 39405126, 2024). "We further illustrate the role of TREM2 in restoring organ homeostasis in sepsis and soluble TREM2 (sTREM2) as a diagnostic marker for sepsis-associated encephalopathy (SAE)." (PMID 38236825, 2024). "In this study, we identified a subset of lipid-associated macrophages characterized by high expression of trigger receptor expressed on myeloid cells 2 (TREM2) and demonstrated that TREM2 acted as a suppressor of FAO to increase the susceptibility to sepsis." (PMID 39405126, 2024). "We found that Trem2-specific deficiency in macrophages exacerbated cardiac dysfunction, myocardial injury and cardiac inflammation following sepsis." (PMID 36635449, 2023). "Trem2 deficiency in NAFLD-associated sepsis mouse models accelerate NAFLD progression, which is consistent with the observation that Trem2 − / − mice fed a HFD exhibited more severe hepatic steatosis." (PMID 35658903, 2022). "We also established a murine model of P. aeruginosa-induced sepsis using TREM2-deficient versus WT C57BL/6 mice, and found that TNF-α expression was comparable between the two groups (data not shown), which is consistent with our observation in this study." (PMID 29887864, 2018). "Notably, TREM2 expression level is reported to decrease in elderly sepsis patients, and TREM2 deficiency in macrophages results in defective anti-bacterial capacity and excessive inflammation." (PMID 40379629, 2025). "Inhibition of FAO abolished the improved sepsis symptoms induced by TREM2 deficiency." (PMID 39405126, 2024). "Since FAO is impaired in sepsis and TREM2 deficiency could alleviate sepsis and improve macrophage FAO, we next explored whether TREM2 regulated sepsis-induced inflammation and organ damage through affecting FAO." (PMID 39405126, 2024).
Sepsis (continued). "Taking these data together, we suggest that TREM2 is associated with FAO defects in sepsis and blocking TREM2 could restore the impaired FAO induced by sepsis." (PMID 39405126, 2024). "Though some clinical data suggest that TREM2 levels may be associated with sepsis severity in patients, clinical data from different populations and different countries are still needed to verify this association." (PMID 38236825, 2024). "To determine whether triglyceride or glucose levels are associated with TREM2-mediated cytokine regulation in sepsis, we further analyzed the correlations between these metabolic parameters and inflammatory cytokines produced by TREM2+ monocytes." (PMID 39405126, 2024). "Our study explored the role of TREM2 in sepsis caused by consecutive LPS injections and suggests that TREM2 might be a novel target for the intervention of neuroinflammation." (PMID 36672106, 2023). "TREM2 deficiency was shown to prevent increases in the brain myeloid cell populations in response to traumatic brain injury, ischemia, aging, and in the initial response to demyelination, though it did increase the number of cells in a model of sepsis." (PMID 28768545, 2017). "Our ex vivo studies suggest that the protective effect of TREM-2 deficiency in part results from the diminished capacity of TREM-2-deficient macrophages to elicit a pro-inflammatory response which is an important contributor to organ injury in the event of sepsis." (PMID 27253382, 2016). "While TREM2 is widely acknowledged for its protective role in immune regulation, excessive activation of TREM2 may yield immunosuppressive effects, potentially impairing immune responses and heightening the risk of secondary infections following sepsis." (PMID 40552184, 2025). "In addition, TREM2 knockout also led to reduced liver and kidney injuries caused by sepsis." (PMID 39405126, 2024). "TREM2 unveils a realm of promising potential in the treatment of sepsis-induced acute lung injury, its central role in immunomodulation and tissue repair establishing it as a formidable therapeutic target." (PMID 40552184, 2025). "This article endeavors to elucidate the intricate interplay between sepsis, lung injury, and TREM2's role in immune modulation." (PMID 40552184, 2025). "We systematically assess the expression levels of TREM2 in sepsis patients and scrutinize its correlation with clinical outcomes, drawing upon current research findings." (PMID 40552184, 2025). "This duality accentuates the significance of TREM2 in maintaining a delicate balance of pro-inflammatory signals, a crucial endeavor to avert excessive tissue damage in the context of sepsis." (PMID 40552184, 2025). "Recent explorations have illuminated TREM2's dual contribution to the regulation of the immune system and its protective influence amidst the inflammatory tempest of sepsis." (PMID 40552184, 2025). "In a cecal ligation and puncture (CLP) sepsis mouse model, single-cell RNA sequencing with fate mapping techniques identified a subgroup of cardiac-resident macrophages highly expressing Trem2 (Trem2hi-CD163+RETNLA+ macrophages)." (PMID 40083551, 2025). "Trigger receptor 2 (TREM2) enhances bacterial clearance by controlling ROS production during sepsis." (PMID 40046257, 2025). "In pathological states such as sepsis, the role of TREM2 is indispensable for immunomodulation and tissue repair." (PMID 40552184, 2025). "Compelling evidence indicates that TREM2 tempers excessive inflammatory responses through the nuanced modulation of macrophage activity and functionality, thereby alleviating the burdens of sepsis-induced acute lung injury." (PMID 40552184, 2025). "In our study, we observed reduced mortality in TREM2–/– mice during a severe CLP polymicrobial sepsis model, bacterial sepsis model, and LPS-induced acute endotoxemia model." (PMID 39959967, 2025).